ZFP41 (ZFP41 zinc finger protein)
Description:
A putative DNA-binding regulatory protein associated with meiosis in spermatogenesis.
Synonyms: Zfp-41; FLJ38705; FLJ00028; ZNF753
Tractability: Antibody: the Human Protein Atlas places it where antibodies can reach. PROTAC: its protein half-life has been measured.
Gene: Protein-coding gene on chromosome 8 (143,246,821 to 143,262,705, forward strand). Ensembl gene ENSG00000181638.
Subcellular location: Nucleus
Subcellular location (Human Protein Atlas): Nucleoli; Nucleoli rim; Nucleoplasm; Plasma membrane
Gene Ontology:
Molecular function: protein binding; sequence-specific double-stranded DNA binding; DNA-binding transcription factor activity, RNA polymerase II-specific; RNA polymerase II transcription regulatory region sequence-specific DNA binding
Biological process: regulation of transcription by RNA polymerase II
Cellular component: nucleus
Genetic constraint (gnomAD): Loss-of-function variants: 10 observed, 11.95 expected, observed/expected ratio (o/e) 0.84, 90% interval 0.51 to 1.41. The upper end of that interval is the gene's LOEUF score, 1.41, which puts it in group 5 of 6, group 1 being the genes least tolerant of losing a copy. Missense variants: 302 observed, 273.7 expected, observed/expected ratio (o/e) 1.1, 90% interval 1 to 1.21. Synonymous variants: 123 observed, 105.56 expected, observed/expected ratio (o/e) 1.17, 90% interval 1.01 to 1.35.
Homologues: Orthologues: chimpanzee ZFP41 (99% identical), macaque ZFP41 (94% identical), rat Zfp41 (81% identical), guinea pig ZFP41 (81% identical), mouse Zfp41 (81% identical), dog ZFP41 (78% identical), zebrafish si:ch1073-224n8.1 (29% identical), zebrafish znf16l (29% identical), zebrafish si:dkey-210j14.3 (28% identical), zebrafish si:dkey-210j14.4 (27% identical), zebrafish si:ch211-284e13.5 (20% identical). Paralogues in human: ZNF22 (34% identical), ZNF430 (24% identical), ZNF98 (24% identical), ZNF257 (23% identical), ZNF92 (23% identical), ZNF675 (23% identical), ZNF680 (23% identical), ZNF253 (22% identical), ZNF273 (22% identical), ZNF723 (22% identical), ZNF737 (22% identical), ZNF730 (21% identical), and 6 more.
Diseases named in the same sentence as ZFP41 in open-access papers:
ZFP41 is named in the same sentence as 3 diseases in open-access papers, as found by Europe PMC text mining. Sharing a sentence is not in itself a finding about the gene and the disease. The quoted sentences say what the papers report.
hepatocellular carcinoma (2 papers, 2025). A malignant tumor that arises from hepatocytes. "Zinc finger protein 41 (ZFP41) can suppress the progression and metastasis of hepatocellular carcinoma, and YTHDF3-catalyzed m6A modification of ZFP41 suppresses hepatocellular carcinoma malignant progression by attenuating Snail transcriptional activation." (PMID 40986143, 2025). "YTHDF3 binds to and degrades ZFP41 mRNA, inhibiting the Snail and EMT pathways and thus suppressing hepatocellular carcinoma metastasis." (PMID 40774945, 2025).
cancer (1 paper, 2024). A tumor composed of atypical neoplastic, often pleomorphic cells that invade other tissues. "To test whether ZFP41 functions as a cancer suppressor through Snail, we established cell lines in which MHCC‐97H stably expresses ZFP41, as well as stably expressing both ZFP41 and Snail." (PMID 39473907, 2024).
tumor (1 paper, 2024). "To conclude, our research demonstrates that ZFP41 expression is reduced in tumor tissues of HCC patients relative to normal tissues, suggesting its potential as an independent prognostic element for HCC patients." (PMID 39473907, 2024). "After 4 weeks, the group with ZFP41 overexpression showed reduced tumor volume and decreased tumor weight relative to the control group." (PMID 39473907, 2024). "After 4 weeks, the group with ZFP41 overexpression showed smaller tumor volume and tumor weight." (PMID 39473907, 2024).